PDX1 (pancreatic and duodenal homeobox 1)
Diseases named in the same sentence as PDX1 in open-access papers (continued):
Sharing a sentence is not in itself a finding about the gene and the disease.
pancreatic neuroendocrine tumor (7 papers, 2009 to 2026). Pancreatic endocrine tumor, also known as pancreatic neuroendocrine tumor (PNET), describes a group of endocrine tumors originating in the pancreas that are usually indolent and benign, but may have the potential to be malignant. "Although PDX-1 immunopositivity was seen in less than 1/3 pancreatic NETs in previous reports, it was positive in 6% of pancreatic NETs in this study probably due to different source of antibodies, since it was positive in all internal controls." (PMID 29713473, 2018). "PDX-1 was overexpressed in 36 human pancreatic and islet neoplasia specimens including 26 pancreatic neuroendocrine tumors and 10 nesidioblastosis specimens." (PMID 22905092, 2012). "Moreover, expression levels of NICD were correlated with those of PDX-1 in human pancreatic neuroendocrine tumor." (PMID 24705209, 2013). "PDX-1 was overexpressed in pancreatic neuroendocrine tumors and nesidioblastosis." (PMID 22905092, 2012). "However, PDX-1 was immunoreactive in only 1 of 17 pancreatic NETs." (PMID 29713473, 2018). "The transcription factors ARX and PDX1, and alternative lengthening of telomeres (ALT) were recently described as prognostic markers for resected non‐functional pancreatic neuroendocrine tumors (PanNETs)." (PMID 31846235, 2020). "In 98 GI and pancreatic NETs, the sensitivity and 95% confidence interval (95% CI) for NKX2.2, PDX-1, and CDX-2 were 84% (95% CI, 75% - 90%), 14% (95% CI, 8% - 23%), and 53% (95% CI, 43% - 63%), respectively." (PMID 29713473, 2018). "In the GI and pancreatic NETs (N = 98), NKX2.2, PDX-1, and CDX-2 were immunoreactive in 82 (84%), 14 (14%), and 52 (52%) cases, respectively." (PMID 29713473, 2018). "PDX-1 was expressed mainly in the small intestinal and appendiceal NETs, occasionally in the pancreatic NETs, and not in the colorectal NETs." (PMID 29713473, 2018).
chronic pancreatitis (6 papers, 2017 to 2026). A chronic inflammatory process causing damage and fibrosis of the pancreatic parenchyma. "Indeed, Pdx1-Cre;HIF2dPA mice develop features reminiscent of chronic pancreatitis including acinar cell loss, acinar-ductal metaplasia, inflammatory cell infiltration, fibrosis and lipomatosis." (PMID 30209343, 2018). "Single-nucleus RNA-seq analyses of pancreatic acinar and ductal cells from neonatal, adult, and chronic pancreatitis donors suggested PDX1 activity alleviates high secretory load and ER-stress in acinar and biases ducts toward homeostatic phenotypes." (PMID 42064940, 2026). "We used a cytokine array to investigate the presence of immunomodulatory factors in tissue lysates of Pdx1-Cre;iASPP+/+, Pdx1-Cre;iASPPΔ8/Δ8, KC and KC;iASPPΔ8/Δ8 pancreata after 6 weeks of mild chronic pancreatitis." (PMID 37270580, 2023). "The observed increase in PDX1 expression of CFTR-KO pancreatic ducts was postulated to be either due to the altered signals from the remodeled pancreatic environment or due to a cell-autonomous change associated with ADM, as often observed in PDX1-positive PDAC caused by chronic pancreatitis." (PMID 39687022, 2024). "We injected 4-week-old Pdx1-Cre;LSL-KrasG12D and Pdx1-Cre;LSL-KrasG12D;EHMT2fl/fl mice with caerulein for 4 weeks to induce repeated chronic pancreatitis." (PMID 34249932, 2021).
exocrine pancreatic insufficiency (5 papers, 2013 to 2024). Inability of the exocrine pancreas to produce and secrete an adequate amount of digestive enzymes into the small intestine. "Homozygous and compound heterozygote mutations in the PDX1 gene have been associated with permanent neonatal diabetes and exocrine pancreatic insufficiency due to pancreatic agenesis." (PMID 38333726, 2023). "The association between AP and the PDX1 gene was previously suggested in a case study of a patient with AP and other related abnormalities including duodenal atresia, hypoplastic gallbladder, permanent neonatal diabetes mellitus, and exocrine pancreatic insufficiency." (PMID 37635636, 2023). "We report a further four cases with biallelic PDX1 mutations without clinical evidence of exocrine pancreatic insufficiency." (PMID 23320570, 2013).
gestational diabetes (5 papers, 2016 to 2025). Carbohydrate intolerance first diagnosed during pregnancy. "The patient’s mother, carrying a normal PDX1 allele and the N196T variant, only had gestational diabetes." (PMID 40485586, 2025).
intrauterine growth restriction (5 papers, 2013 to 2024). "Intrauterine growth restriction has been associated with progressive epigenetic silencing of Pdx1, a pancreatic and duodenal homeobox 1 transcription factor critical for β-cell development, resulting in impaired β-cell function and T2D in the adult offspring in rats." (PMID 23382021, 2013). "Accordingly, a study with intrauterine growth restriction showed that these male pups have increased Pdx1 methylation." (PMID 38673723, 2024). "Rats faced with intrauterine growth restriction had permanently reduced expression of Pdx1 in β cells and developed type 2 diabetes in adulthood." (PMID 23476780, 2013). "Another example of environmentally-induced epigenetic changes is reduced pancreatic and duodenal homeobox 1 (Pdx1), also known as insulin promoter factor 1, in a rat model of intrauterine growth restriction." (PMID 23476780, 2013).
neonatal diabetes mellitus (5 papers, 2019 to 2025). Neonatal diabetes mellitus presents as hyperglycemia, failure to thrive and, in some cases, dehydration and ketoacidosis which may be severe with coma, in a child within the first months of life. "Six patients of Group 2 carried a pathogenic or likely pathogenic variant in KCNJ11 (3 variants), ABCC8 (1 variant) and PDX1 (biallelic variants); a patient with transient neonatal diabetes mellitus had 6q24 methylation defects (Online resource 1, left panel)." (PMID 36178555, 2023).
neuroendocrine tumors (5 papers, 2012 to 2026). "The expression of CDX2 and PDX1 is highly specific for identifying neuroendocrine tumors of intestinal origin, since bronchopulmonary carcinoids seem to be negative for these two markers." (PMID 22269186, 2012). "Unlike the NKX2.2, PDX-1, and CDX-2 that had restricted expression pattern in NETs of different site, PTF1A was expressed in all normal and neuroendocrine tumor cells (data not shown)." (PMID 29713473, 2018).
colon cancer (4 papers, 2017 to 2025). "According to the proliferation assay, pancreatic and colon cancer cells’ ectopic expression of the PDX1 gene increased their growth rate." (PMID 34503200, 2021). "The least pronounced effect of PDX1 expression on proliferative activity was observed in SW620 colon cancer cells." (PMID 34503200, 2021). "Notably, PDX1 and GNG7 were common to both rectal and colon cancer analyses, with GNG7 also ranking among the top ten genes in colon cancer." (PMID 40565513, 2025).
diabetic retinopathy (4 papers, 2021 to 2024). "We have previously shown that, starting at three months of age, pdx1 mutants exhibit not only vascular but also neuro-retinal pathologies manifesting as photoreceptor dysfunction and loss, similar to human diabetic retinopathy." (PMID 34831487, 2021). "The pdx1 homozygous mutant zebrafish was a novel and clinically relevant model for diabetic retinopathy at the date it was reported." (PMID 38279951, 2024). "In conclusion, this study revealed that diabetic retinopathy in the pdx1 diabetic zebrafish features not only neural pathologies, but also a restorative response based on the enhanced regenerative properties of the zebrafish retina." (PMID 34831487, 2021). "Moreover, the pdx1 mutant is a valuable resource for molecular studies to identify new targets for the treatment of early as well as late diabetic retinopathy." (PMID 38279951, 2024). "Samples in the remaining two studies are urine from rats and the whole body of 50 pdx1−/− zebrafish, which is a model for diabetic retinopathy lacking the transcription factor pdx1." (PMID 36557282, 2022).
invasive carcinoma (4 papers, 2010 to 2023). A carcinoma that is not confined to the epithelium, and has spread to the surrounding stroma. "Although the KC (Pdx1-Cre; LSL-KrasG12D) mouse model also involves the induction of pancreatic intraepithelial neoplasia (PanIN) and invasive carcinoma, the incidence of the latter is lower than in KPC mice." (PMID 28407685, 2017). "The invasive carcinomas that developed in p16−/−; LSL- KrasG12D; Pdx1-Cre mice involved extensive amounts of peripancreatic tissue and frequently formed metastases." (PMID 22113502, 2011). "Adenocarcinomas were identified in 21of 22 invasive carcinomas in p16−/−; LSL- KrasG12D; Pdx1-Cre mice and comprised ≥ 50% in 13 of the 21 invasive carcinomas and in 9 of 9 in p16flox/flox; LSL- KrasG12D; Pdx1-Cre mice and comprised ≥ 50% in 5 of the 9 in p16flox/flox; LSL- KrasG12D; Pdx1-Cre mice." (PMID 22113502, 2011). "Whereas ∼40% of total tumors could be classified as invasive carcinomas in control mice, greater than 60% of all tumors fell into this category in RT2+; Pdx1-CreER+; DspFlox/Flox mice." (PMID 20862307, 2010).
neuroblastoma (4 papers, 2020 to 2023). Neuroblastoma (NB) is the most common solid, extracranial childhood tumor. "Some of the genes identified as changing in PDX5 versus PDX1 are related to this molecular function, including, for the first time in this work, some genes that have been associated with survival in neuroblastoma patients." (PMID 36675105, 2023). "When PBPC products with 10% contaminating neuroblastoma cells were used, we observed that an increase of 25 ± 1% of the main transducer voltage relative to calibration settings resulted in a relative recovery of 98.4 ± 0.47% of PDX-1 cells in the center (tumor cell) outlet." (PMID 34654486, 2021).
acute pancreatitis (3 papers, 2023 to 2024). An acute inflammatory process that leads to necrosis of the pancreatic parenchyma. "Conversely, downregulated DEGs in the Pdx1-Ehmt2fl/fl and P48-Ehmt2fl/fl acute pancreatitis models were only significantly enriched for networks that signal KRAS down." (PMID 38948355, 2024). "We tested iASPP function in acinar cells, the purported PC cell-of-origin, and assessed this using Pdx1-Cre;iASPPΔ8/Δ8 mice in the acute pancreatitis and recovery model." (PMID 37270580, 2023). "PCA demonstrated that animals with intact Ehmt2 clustered together during the acute pancreatitis treatment regardless of the model, Pdx1 or P48Cre/+, and separated from their Ehmt2fl/fl counterparts." (PMID 38948355, 2024).
ductal adenocarcinoma (3 papers, 2009 to 2023). "However, neither non-β-cell endocrine neoplasms nor PanINs have been observed, even though Pdx1+ precursors give rise to these cells, and other oncogene models targeting Pdx1+ precursors produce PanINs and infiltrating ductal adenocarcinomas." (PMID 19812721, 2009).
Pancreatic cysts (3 papers, 2013 to 2021). A cyst of the pancreas that possess a lining of mucous epithelium. "In Pdx1-Cre;Vhlh f/f mice with pancreatic-specific loss of Vhlh, pancreatic cysts were observed after 16 to 18 months." (PMID 23384121, 2013). "A bilayer of SMA-positive cells with intercalated Tuj1-positive cells (indicative of the presence of neural cells), features characteristic of gut mesenchyme, was observed in some big pancreatic cysts in Pdx1-Cre; Ctnnb1tm1Mmt/+ mice." (PMID 27736991, 2016). "At 3 mo and older, 34.5% KJC mice (n = 29) and 10.5% KrasLSL-G12D/+;Jag1flox/+;Pdx1-Cre mice (n = 19) showed distended abdomen because of large-size pancreatic cysts containing clear to straw-colored fluid, highlighting the importance of the gene dosage in this SCN/IPMN phenotype." (PMID 33268505, 2021).
Sepsis (3 papers, 2024 to 2025). Sepsis is defined as life-threatening organ dysfunction caused by a dysregulated host response to infection. "I-1 and I-3, who were homozygous for variants predicted to result in complete loss of PDX1, died of sepsis following multiorgan failure and worsening liver function, respectively." (PMID 39542526, 2024).
cognitive deficits (2 papers, 2016 to 2025). "In this study, we demonstrate that Pdx1+/− mice exhibit worsening of cognitive deficits of the APP/PS1 mouse; however, the Pdx1+/− mice did not exhibit a significant deterioration in memory performance compared with that of the WT mice." (PMID 27406855, 2016).
cyst (2 papers, 2009 to 2012). A sac-like closed membranous structure that may be empty or contain fluid or amorphous material. "To investigate whether loss of Vhl in the exocrine pancreas can lead to cyst development, we utilized pancreatic and duodenal homeobox 1 (Pdx1) transgenic mice in which cre recombinase expression was driven by the Pdx1 promoter." (PMID 19340311, 2009). "In order to examine the effect of Notch1 deletion on cyst formation, we utilized PDX-1-Cre;Notch1lox/lox mice, which allow for conditional deletion of Notch1lox/lox alleles specifically in pancreatic epithelial cells at day 8.5 of embryonic development." (PMID 23284900, 2012).
ductal carcinoma (2 papers, 2022 to 2023). "BRD7552 was found as a PDX1 inducer in human ductal carcinoma cell line PANC-1 and primary human islets." (PMID 37843554, 2023). "Although Pdx-1 also expresses out of pancreatic, forced expression of KrasG12D in the liver or colon cannot induce carcinoma or ductal carcinoma." (PMID 35326559, 2022).
gastric adenocarcinoma (2 papers, 2022 to 2023). "Here, we found no gastric carcinogenesis in transgenic mice expressing T antigen in pit and parietal cells, while we observed gastric adenocarcinomas in K19- or PGC-cre/T antigen mice, and gastric adenoma in Pdx1-cre/T antigen mice." (PMID 37247123, 2023). "We also identified gastric adenocarcinomas in one PP and two DPP mice, consistent with previous data indicating Pdx1-CreTg activity in the antral stomach." (PMID 35976056, 2022).
glioma (2 papers, 2022 to 2023). A benign or malignant brain and spinal cord tumor that arises from glial cells (astrocytes, oligodendrocytes, ependymal cells). "The LASSO regression model was constructed to screen the molecular models related to glioma prognosis, which were composed of SYT1, CREB3L3, ITPR1, RASGRF2, PDX1, and RASGRF1." (PMID 37090987, 2023). "Nomogram and calibration curves further confirmed that the prognostic model composed of SYT1, CREB3L3, ITPR1, RASGRF2, PDX1, and RASGRF1 has good stability and potential application value for poor prognosis in patients with glioma." (PMID 37090987, 2023). "Interestingly, the imbalance of oxidative stress-related pathways was also exhibited in glioma tissues, and the expression of SYT1, CREB3L3, ITPR1, RASGRF1, RASGRF2, and PDX1 were significantly different from that of para-cancerous tissues." (PMID 37090987, 2023).
hepatocellular carcinoma (2 papers, 2018 to 2022). A malignant tumor that arises from hepatocytes. "Among these, the homeobox transcription factors Goosecoid and PDX1 have been previously shown to be involved respectively in EMT/metastasis of breast and liver carcinomas and in pancreatic tumorigenesis and metastasis formation." (PMID 35260172, 2022).
lymphoma (2 papers, 2021 to 2022). A malignant (clonal) proliferation of B- lymphocytes or T- lymphocytes which involves the lymph nodes, bone marrow and/or extranodal sites. "The lymphoma phenotype of thymic tumoral mass, as well as the expression of KrasG12D in all thymic cells (including lymphocytes) suggested that recombination could occur independently from Pdx1 expression." (PMID 34302028, 2021).
malnutrition (2 papers, 2017 to 2018). Inadequate nutrition resulting from poor diet, malabsorption, or abnormal nutrient distribution. "The developmental retardation of PDX1-null pups is likely attributable to malnutrition resulting from a lack of digestion in the absence of the pancreas and functional rostral duodenum and/or diabetic consequences due to the absence of the pancreas." (PMID 29383175, 2017).
metastatic carcinoma (2 papers, 2019 to 2025). A carcinoma which has spread from the original site of growth to another anatomic site. "Elevated PDX-1 expression has been observed in malignant tumors of the pancreas, breast, colon, prostate, and kidney, as well as in metastatic cancers." (PMID 40310348, 2025). "Activation of the Pdx1::Cre initiates pancreatic neoplasia, developing into aggressive metastatic carcinoma with a half time of around 150 days." (PMID 31668663, 2019).
nesidioblastosis (2 papers, 2012 to 2023). "However, the key pancreatic transcription factors NK6 homeobox 1(Nkx6.1) and pancreatic and duodenal homeobox 1 (PDX1), as well as GLP-1, showed no abnormalities in nesidioblastosis patients." (PMID 37371827, 2023).
pancreatic NEN (2 papers, 2022 to 2025). "Detailed characterization of pulmonary NEC, pulmonary carcinoid, pancreatic NEN, ileal NEN, and MiNEN was performed using immunohistochemical staining to detect pan-cytokeratin (panCK), Thyreoglobulin (TG), Calcitonin (CT) and the transcription factors CDX2, SATB2, TTF1, GATA3, ARX and PDX1." (PMID 41145514, 2025).
papilloma (2 papers, 2010 to 2021). A benign epithelial neoplasm that projects above the surrounding epithelial surface and consists of villous or arborescent outgrowths of fibrovascular stroma. "However, Pdx1 has already been shown to be expressed in skin, linked to the development of papillomas in KC mice." (PMID 34302028, 2021). "As papilloma development in Pdx1-Cre mice usually occurred in regions susceptible to grooming, scratching and wounding, we speculated that PDX1 expression may be induced in wounded skin triggering Cre-mediated KrasG12D activation and Notch1 ablation." (PMID 21042537, 2010). "Most tumors encountered in Pdx1-Cre;Kras;N1ko mice were benign papillomas but often grew large and ulcerating, requiring euthanasia of animals for ethical reasons." (PMID 21042537, 2010). "In KrasG12D-induced tumorigenesis inhibition of p21 via Myc activation, observed in Pdx1-Cre;Kras;N1ko papillomas, is a critical step for malignant transformation." (PMID 21042537, 2010). "Physiological PDX1 expression in the epidermis does not explain the stochastic character of papilloma formation in the Pdx1-Cre;Kras,N1ko mice." (PMID 21042537, 2010).
skin papilloma (2 papers, 2010 to 2015). A benign papillary neoplastic growth on the skin composed of epithelial cells and a fibrous stalk. "Surprisingly, Pdx1-Cre;Kras;N1ko mice developed focal skin hyperplasia at 10–15 days of age and as early as 4 weeks of age developed massive skin papillomas." (PMID 21042537, 2010). "In addition to PanIN lesions, KC mice are prone to develop skin papillomas in the face and vulvar tissues due to Cre expression by Pdx-1 in these tissues." (PMID 26452271, 2015). "Surprisingly, mice with activated KrasG12D and Notch1 but not Notch2 ablation developed skin papillomas progressing to squamous cell carcinoma providing evidence for Pdx1 expression in the skin." (PMID 21042537, 2010).
acinar cell carcinoma (1 paper, 2009). "In contrast, induction of PyMT in early pancreatic progenitor cells under the control of Pdx1 produces acinar cell carcinomas and β-cell hyperplasia." (PMID 19812721, 2009). "One Pdx1-tTA; tet-o-PyMT-IRES-Luc mouse with acinar cell carcinomas also showed β-cell hyperplasia, but in most cases acinar cell carcinomas apparently arose sooner than β-cell hyperplasia and overwhelmed the whole pancreas." (PMID 19812721, 2009). "A few (less than 10%) of Pdx1-tTA; tet-o-PyMT-IRES-Luc bitransgenic mice developed lethal acinar cell carcinomas in adulthood when the PyMT transgene was induced during embryonic pancreatic development." (PMID 19812721, 2009).
adenoma (1 paper, 2017). A neoplasm arising from the epithelium. "KrasLSL-G12D/+;Pdx1-Cre mice form early onset adenoma in the gallbladder and adjacent biliary tract with complete penetrance, albeit short of invasive adenocarcinoma." (PMID 29142904, 2017).